MYC (MYC proto-oncogene, bHLH transcription factor)
Diseases named in the same sentence as MYC in open-access papers (continued):
Sharing a sentence is not in itself a finding about the gene and the disease.
myeloid neoplasm (24 papers, 2014 to 2026). Proliferation of myeloid cells originating from a primitive stem cell. "Double minutes (dmins), a form of extrachromosomal DNA (ecDNA), represent a rare cytogenomic event in myeloid neoplasms and are most commonly associated with amplification of oncogenes such as MYC or KMT2A." (PMID 41982344, 2026). "IFN-γ-induced association of p27 with MYC at chromatin correlated with loss of total and Ser-62-phosphorylated MYC from target promoters, reduced expression of MYC target genes, growth arrest, differentiation and induction of senescence in myeloid tumor cells." (PMID 28665315, 2017). "When MYC rearrangements do occur in myeloid neoplasms, they frequently correlate with aggressive disease." (PMID 41008781, 2025). "MYC is a major driver for many (perhaps most) lymphoid and myeloid tumours and indeed a variety of solid tumours." (PMID 36755068, 2023). "Further investigation indicated TRAF6 mediates ubiquitination of MYC protein and plays a role of tumor suppressor in myeloid neoplasms, suggesting the decreasing gradient of TRAF6 expression was related to leukemic transformation risk." (PMID 37953918, 2023). "Molecular investigation of dmins in myeloid neoplasms revealed that the most commonly reported dmin is due to the amplification of MYC gene." (PMID 34194582, 2021). "The genetic profile of these MYC- translocated T-ALL is characterized by concomitant abnormalities, including CDKN2A/B deletions, PTEN inactivation, and mutations typical of myeloid neoplasms, such as DNMT3A." (PMID 32185137, 2020). "As previously reported, both MYC targets and E2F targets are characterized by a proliferation signature, and dysregulation of these pathways has been witnessed in a wide variety of cancers, including myeloid neoplasms." (PMID 38253683, 2024). "Unlike lymphoid malignancies, where MYC overexpression is mostly associated with its translocation, the cause of MYC aberrant expression and activity in myeloid malignancies is not thoroughly established." (PMID 34372899, 2021). "Some case reports identified MYC or MLL gene amplification performing as dmin in myeloid neoplasms." (PMID 34194582, 2021). "Moreover, since prior reports showed that TLR2-TRAF6 activation suppresses oncogenic MYC activity in myeloid malignancies, we tested whether the TLR2 agonist CU-T12-9 reduces MYC’s association with the FBXO11 promoter." (PMID 41542766, 2026). "What is noteworthy is that MYC rearrangement is found not only in BL and HGBL with MYC and BCL2 and/or BCL6 rearrangements but also in DLBCL, FL, PBL, B-LBL/ALL, and even in myeloid tumors." (PMID 37182167, 2023). "c-MYC is required to maintain the balance between self-renewal and differentiation of hematopoietic stem cells (HSCs); not surprisingly, c-MYC is commonly overexpressed in both solid and hematopoietic malignancies (both lymphoid and myeloid neoplasms)." (PMID 36536122, 2023).
acute leukemia (23 papers, 2008 to 2025). A clonal (malignant) hematopoietic disorder with an acute onset, affecting the bone marrow and the peripheral blood. "Translocations that give rise to MLL1 fusion proteins can cause acute leukemias due to sustained homeobox gene expression and MYC recruitment to chromatin." (PMID 40378956, 2025). "Apart from that, there are reports on the enhancer-mediated MYC regulatory function of SWI/SNF in Acute Leukemia maintenance." (PMID 31932624, 2020). "In conclusion, this report describes a novel mechanism of resistance to AZD1775 in three acute leukemia cell lines mediated by increased HDAC activity leading to increased c-MYC expression and activity." (PMID 32195191, 2020). "Collectively, these studies indicate HDAC-mediated overexpression of c-MYC drives resistance to AZD1775 in acute leukemia cells." (PMID 32195191, 2020). "A critical requirement on SMARCA4 in promoting MYC-dependent transcription has been described in SMARCA2-proficient acute leukemia cell models." (PMID 31406271, 2019). "In line with reported outcomes for BET inhibitors JQ1 and I-BET in acute leukemia and other hematologic malignancies, OTX015 also decreased c-MYC mRNA or protein as shown in the majority of the cell lines, as well as in primary acute leukemia samples." (PMID 25989842, 2015). "We observed an inverse correlation between levels of c-MYC mRNA and miR-27a, miR-23a, and miR-24 expression in normal CD34+ HSPCs and acute leukemias, suggesting that c-MYC contributes to the regulation of the miR-23a cluster in the hematopoietic system." (PMID 23236401, 2012). "Thus, in combination with AraC, memantine fosters inhibition of AKT, ERK1/2 and MYC signaling in Jurkat cells, key regulators of proliferation and survival in acute leukemia." (PMID 30651113, 2019). "Decreased miR-23a cluster expression in some acute leukemia cell lines was mediated by c-MYC." (PMID 23236401, 2012). "Finally, we observed a significant inverse correlation between c-MYC mRNA and mature miR-27a levels in human acute leukemias; a similar inverse correlation between c-MYC and miR-23a and miR-24 was also observed." (PMID 23236401, 2012). "c-MYC was shown to be hypomethylated in acute leukemia derived from myelodysplastic syndromes." (PMID 18698372, 2008). "Conversely, NPM1 gene mutations result in genomic instability, loss of tumor suppressor function, inhibition of normal cell apoptosis, upregulation of MYC protein expression, abnormal expression of HOX genes, ultimately leading to the occurrence of acute leukemia." (PMID 39432585, 2024). "In KMT2A-rearranged acute leukemia, sensitization following curaxin and panobinostat treatment is mediated by increasing histone acetylation, decreasing MYC expression, and not by altered expression of target genes HOXA9 and MEIS1." (PMID 37370721, 2023). "Our conclusion is that while BRD9 may play a role in maintenance of MYC expression in some acute leukemia and MM cells, it does not play a universal role in maintenance of MYC expression." (PMID 35853853, 2022). "Thus, evidence suggests that the miR-23a cluster is transcriptionally regulated by c-MYC and is not genetically deleted in the majority of acute leukemias." (PMID 23236401, 2012).
Ewing sarcoma (23 papers, 2011 to 2026). A small round cell tumor that lacks morphologic, immunohistochemical, and electron microscopic evidence of neuroectodermal differentiation. "The interplay between EWS-FLI-1 and MYC represents a central driver of Ewing’s sarcoma pathogenesis." (PMID 40076599, 2025). "A link between SYK and MYC has been previously demonstrated in Ewing sarcoma and hematopoietic cells." (PMID 30744170, 2019). "To verifythe novel prediction that MYC protein plays a functional role in Ewing tumor, we assessedthe phenotype changes of independent Ewing sarcoma cell lines on MYCknockdown." (PMID 23457041, 2013). "We demonstrate ChIP-PED using a number of examples,including a novel discovery that MYC, a human TF, plays an importantfunctional role in pediatric Ewing sarcoma cell lines." (PMID 23457041, 2013). "Although Ewingtumor has been previously shown to exhibit high-MYC expression, thefunctional role of MYC protein in Ewing tumor currently remains uncharacterized." (PMID 23457041, 2013). "In addition, a series of experiments using mouse and human cell models for Ewing sarcoma associated the gain of chromosome 8 with the up-regulation of the RAD21 and MYC genes that reside on that chromosome." (PMID 36859339, 2023). "Interestingly, c-MYC was also reported to transcriptionally activated MALAT1 by binding to MALAT1 promoter, which contributes to a novel SYK/c-MYC/MALAT1 pathway to promote Ewing Sarcoma." (PMID 30683916, 2019). "Next, expression levels of eight EWS-FLI1 associated target genes (GLI1, NEX2.2, CyclinD, c-MYC, NR01B, IGF1R, EZH2, and CD99) which were known to be upregulated, and three genes (FOXO1, IGFBP3, and LOX) known to be down regulated in Ewing’s sarcoma was assessed." (PMID 28775288, 2017). "This approach generated a total of 147 genes, containing a number of known Ewing sarcoma oncogenes such as CCND1, NKX2–2, BCL11B and MYC." (PMID 30496486, 2019). "BET inhibitors (BETi), such as JQ1, have demonstrated antitumor activity in several fusion-driven sarcomas, including rhabdomyosarcoma (RMS) and Ewing sarcoma (ES), by disrupting BRD4-dependent transcriptional activity, reducing oncogene expression (e.g., MYC), and impairing super-enhancer function." (PMID 41166819, 2025). "Furthermore, CDK12 also lethally interacts with proto-oncogenes such as MYC and EWS/ FLI (Ewing sarcoma (ES) oncoprotein) and these interactions also provide an opportunity for a therapeutic target." (PMID 33868579, 2021). "Moreover, in the same study, in Ewing sarcoma, exposure to PU-H71 resulted in depletion of critical proteins, including AKT, pERK, Raf-1, c-MYC, c-KIT, IGF1R, hTERT, and EWS-FLI78." (PMID 32895397, 2020). "Furthermore, xenograft of control and shMYC TC71 Ewing sarcoma cellsinto immunodeficient mice (NOD/SCID/IL-2γ null) resulted in a significant decreasein volume and weight for the MYC knockdown tumors after 6 weeks of growth." (PMID 23457041, 2013). "Because IER3 is a modulator of apoptosis through TNFalpha or FAS-signaling, the balance between its repression (through MYC, E2F2 and E2F5 that are EWS-FLI1 induced and therefore disease specific) and activation (through NFkB) may be of particular interest in Ewing sarcoma." (PMID 23935076, 2013).
prostate adenocarcinoma (23 papers, 2010 to 2025). "We also tested SMYD3 abundance in a genetically engineered mouse model that recapitulates the development of human lethal prostate adenocarcinoma and metastasis through MYC overexpression and loss of Pten in prostatic luminal epithelial cells (Hoxb13-MYC+/− Hoxb13-Cre+/−PtenFl/Fl, or BMPC mice)." (PMID 37976356, 2023). "We first examined correlations between MYC protein levels and complex I gene expression across prostate adenocarcinoma (PRAD) samples." (PMID 40668928, 2025). "In advanced prostate adenocarcinoma, MYC signaling is one of the most activated pathways, and alterations in MYC gene loci occur already in the early phase." (PMID 36969025, 2023). "In here, we cross-bred the transgenic miR-32-expressing mice with a genetic model initiating prostate adenocarcinoma by expression of the MYC oncogene." (PMID 35228520, 2022). "Here, we cross-bred these mice with the hiMYC model mice overexpressing oncogenic MYC prostate-specifically, thereby inducing prostate adenocarcinoma with high penetrance." (PMID 35228520, 2022). "In conclusion, we show that miR-32 promotes MYC-induced prostate adenocarcinoma and identifies PDK4 as a PC-relevant metabolic target of miR-32-3p." (PMID 35228520, 2022). "Our work shows that miR-32 contributes to the regulation of Msmb levels in MYC-induced adenocarcinoma of the prostate." (PMID 35228520, 2022). "In the Prostate Adenocarcinoma (TCGA, Firehose Legacy) and Liver Hepatocellular Carcinoma (TCGA, PanCancer Atlas) datasets, MYC mRNA was highly expressed in the INTS14 mRNA high-expression group." (PMID 35887071, 2022). "PTENpc−/−/Hi-MYC bigenic mice have large prostatic adenocarcinomas at 3 months, well in advance of either of the well-established single lesion models, which at this stage harbor mPIN exclusively." (PMID 21394210, 2011). "Indeed, several of these, most notably MYC and PRC2 activity, have been implicated across multiple prior studies, including in of lung and prostate adenocarcinomas to aggressive small cell neuroendocrine tumors." (PMID 34656143, 2021). "Further, marked overexpression of MYC protein occurs in the nuclei of the majority of primary prostatic adenocarcinomas, as well as, exclusively within the luminal compartment of high-grade PIN lesions, the presumptive precursor to many prostatic adenocarcinomas." (PMID 20195545, 2010). "In addition, double-label immunofluorescence in human prostatic adenocarcinoma for MYC and Ki67 reveal a discordance in many of the cells (AM De Marzo, Uzoma Anele, MengMeng Xu, unpublished observations)." (PMID 20195545, 2010). "Further, The Cancer Genome Atlas data (TCGA) independent database was used for validation of key genes EGFR, MYC, VEGFA, PTEN expression in prostate adenocarcinoma." (PMID 35456461, 2022). "Lo-MYC and Hi-MYC mice develop prostatic intraepithelial neoplasia (PIN) and prostatic adenocarcinoma as a result of MYC overexpression in the mouse prostate." (PMID 20195545, 2010). "Since MYC is known to be consistently overexpressed in human PIN (compared with normal prostate luminal cells) and most primary and metastatic castration-resistant prostatic adenocarcinomas, these findings implicate MYC overexpression as causing mtDNAcn increases in these lesions." (PMID 37971875, 2023). "Further, within prostate adenocarcinomas of PCAWG cohort, 17 tumors had A/A genotype, only 2 were with A/T and none were with T/T genotype but, similar to the observation in the pan-cancer data, the expression of PCAT1, PVT1, and MYC was found to be higher in those with A/T genotypes." (PMID 32680982, 2020).
prostatic intraepithelial neoplasia (23 papers, 2008 to 2024). "Focal c-MYC expression resulted in mild pathology, but prostate-specific deletion of a single allele of the Pten tumor suppressor gene cooperated with c-MYC to induce high grade prostatic intraepithelial neoplasia (HGPIN)/cancer lesions." (PMID 19578399, 2009). "Overexpression of MYC in the prostate results in prostatic intraepithelial neoplasia (PIN) with progression to invasive adenocarcinoma." (PMID 36970725, 2022). "In one study in which MYC was overexpressed in the prostate of engineered mice, it was found that prostatic intraepithelial neoplasia progressed to invasive adenocarcinoma, demonstrating the oncogenic role of MYC in PCa." (PMID 33281882, 2020). "Overexpression of MYC mRNA has been found in both prostate intraepithelial neoplasia and carcinomas, and overexpression of MYC protein has been reported as an early alteration in human prostate carcinogenesis." (PMID 33318499, 2020). "One study overexpressed MYC in the prostate of engineered mice and found that prostatic intraepithelial neoplasia progressed to invasive adenocarcinoma, demonstrating the oncogenic role of MYC in PCa." (PMID 33281882, 2020). "Although MYC expression has been observed in the cancer precursor high-grade prostatic intraepithelial neoplasia, MYC expression in indolent-appearing tumor cells predicts the presence of higher-grade disease and is associated with poor differentiation." (PMID 32681068, 2020). "However, even in the stage of prostate intraepithelial neoplasia, an increase in the number of copies of the MYC gene can be observed." (PMID 37664042, 2023). "MYC is a well-established proto-oncogene that drives the tumorigenesis of PCa, and its activation was reported to be one of the first changes that occur just before or during the onset of prostate intraepithelial neoplasia." (PMID 36033512, 2022). "As well as driving the formation of prostate intraepithelial neoplasia, overexpression of TF MYC could further suppress target gene HSH2D." (PMID 35164166, 2022). "This hypothesis was supported by experimental studies showing that MYC hyperexpression in prostate epithelial cells determines the formation of prostate intraepithelial neoplasias and induces a downmodulation of NKX3.1 expression." (PMID 31366128, 2019). "In the Hi-MYC model, the modified (ARR2PB) probasin promoter-driven expression of human MYC in the prostate results in murine prostate intraepithelial neoplasia (mPIN) in the lateral prostate (LP) by 4 weeks of age that progresses to adenocarcinoma in all mice by 6–9 months." (PMID 21394210, 2011).
acute promyelocytic leukemia (22 papers, 2011 to 2025). An aggressive form of acute myeloid leukemia (AML), characterized by arrest of leukocyte differentiation at the promyelocyte stage, due to a specific chromosomal translocation t(15;17) in myeloid cells. "A unique lncRNA, PVT1, has been involved in acute promyelocytic leukemia (APL) through promoting cell proliferation by MYC." (PMID 30466456, 2018). "Knockdown MYC in human promyelocytic leukemia cells resulted in down-regulation of PVT1 supporting our analysis that MYC could bind to the putative promoter of PVT1." (PMID 34940755, 2021). "Moreover, myelocytomatosis oncogene (MYC) inhibits miR-29b expression in acute promyelocytic leukemia cells and participates in the mediation of miR-29b in bone marrow differentiation." (PMID 33228517, 2020). "Moreover, MYC has been highlighted to be a target gene of miR-29b, and inhibition of miR-29b impairs neutrophil differentiation of acute promyelocytic leukemia cells through regulating MYC expression." (PMID 33228517, 2020). "Tosedostat down regulated five of nine enriched genes in the V$E2F_01 promoter motif signature in HL-60 cells (acute promyelocytic leukemia) where down regulation of MYC could impact a large number of TN enriched genes." (PMID 26005638, 2015). "To date, it has been shown that the c-MYC protein inhibits erythroid differentiation in the K562 cell line, while the anti-c-MYC DNA oligomer induces granulocytic differentiation of human promyelocytic leukemia HL-60 cells in both serum-containing and serum-free media." (PMID 38967692, 2024).